RNU6-258P (RNA, U6 small nuclear 258, pseudogene)
Gene: Small nuclear RNA gene on chromosome 17 (20,126,388 to 20,126,488, reverse strand). Ensembl gene ENSG00000212186.
Homologues: Orthologues: chimpanzee U6 (99% identical), macaque U6 (91% identical), pig U6 (70% identical), rat LOC120100188 (67% identical), pig U6 (63% identical), pig U6 (59% identical). Paralogues in human: RNU6-621P (79% identical), RNU6-669P (79% identical), RNU6-393P (78% identical), RNU6-854P (78% identical), RNU6-1060P (77% identical), RNU6-140P (77% identical), RNU6-274P (77% identical), RNU6-41P (77% identical), RNU6-820P (77% identical), RNU6-853P (77% identical), RNU6-1024P (76% identical), RNU6-1091P (76% identical), and 1284 more.